IFNG (interferon gamma)
Diseases named in the same sentence as IFNG in open-access papers (continued):
Sharing a sentence is not in itself a finding about the gene and the disease.
bovine tuberculosis (37 papers, 2013 to 2025). "The Single Intradermal Comparative Tuberculin Test (SICTT) and the interferon-gamma (IFN-γ) assay are the approved diagnostic tests for bovine tuberculosis (bTB) in Ireland." (PMID 37589815, 2024). "The higher vulnerability of Mediterranean buffaloes to bovine tuberculosis was associated with an SNP (G > A) at position 4467 in the 3′ UTR of the interferon-gamma (IFNG) gene, which caused the target sequence disruption for the micro-RNA (miR-125b)." (PMID 33809937, 2021). "Tuberculin based tests (tuberculin skin test and the interferon gamma assay) have since been used as diagnostic tools for bovine tuberculosis." (PMID 27375559, 2016). "It is also potentially important to test the effect of exposure of animals to NTM on the specificity and/or sensitivity of bovine tuberculosis (bTB) diagnostic test such as skin test and interferon gamma assay due to potential cross-reactivity." (PMID 25403612, 2014). "In Spain, the national bovine tuberculosis (bTB) eradication program is based on yearly skin testing of every ≥6 weeks old animal using the single or comparative tuberculin test and parallel use of the interferon-gamma (IFN-γ) assay as an ancillary diagnostic test in infected herds." (PMID 30320129, 2018). "Diagnosis of bovine tuberculosis has relied on examinations of cell-mediated immune responses to M. bovis proteins using tuberculin skin testing and/or interferon gamma release assays." (PMID 39195811, 2024). "In Spain, the single intradermal tuberculin (SIT) test and interferon-gamma (IFN-γ) assay are used to diagnose bovine tuberculosis in official eradication programmes." (PMID 29142508, 2017). "The Delayed type hypersensitivity skin test (DTH) and interferon-gamma assay are used for the diagnosis of bovine tuberculosis (TBB)." (PMID 25110654, 2014). "Bovine tuberculosis is usually diagnosed using tuberculin skin and interferon gamma tests." (PMID 37804385, 2024). "Additionally, two cattle from a commercial dairy farm were bovine tuberculosis (bTB) positive using the bTB skin test and confirmatory interferon-gamma assay." (PMID 37342558, 2023). "Ante-mortem bovine tuberculosis (bTB) tests for buffaloes include the single comparative intradermal tuberculin test (SCITT), interferon-gamma (IFN-γ) release assay (IGRA) and IFN-γ-inducible protein 10 release assay (IPRA)." (PMID 36558727, 2022). "The diagnosis of bovine tuberculosis (bTB) is based on the single intradermal tuberculin test (SIT), interferon gamma, and compulsory slaughter of reactor animals." (PMID 35647097, 2022). "The interferon-gamma (IFN-γ) assay and single comparative cervical skin test (SCITT) are used to estimate bovine tuberculosis (bTB) prevalence globally." (PMID 35873684, 2022).
Chronic colitis (37 papers, 2009 to 2025). A chronic inflammatory disease of the large intestine (colon, cecum and rectum). "Another species of Parabacteroides, Parabacteroides distasonis, also demonstrated anti-inflammatory properties by preventing an increase in pro-inflammatory cytokines such as IFNγ, IL-12, IL-17 and IL-16 in mice after induced acute or chronic colitis." (PMID 37504910, 2023). "Similarly to previous reports, progression from acute to chronic colitis in wt mice was associated with a reduced expression of IFNγ and IL-6, accompanied by an increased (albeit not significant) IL-10 levels." (PMID 20706593, 2010). "In another chronic colitis model of IL-10−/− mice investigating prophylactic as well as therapeutic treatment regimens with SC doses ranging from 0.01–10 mg/kg, reductions in histopathology scores and TNF-α as well as interferon-gamma (IFN-γ) levels measured in colonic organ cultures were seen." (PMID 32545207, 2020).
gastritis (37 papers, 2008 to 2026). Inflammation of the stomach. "IFNγ plays a major role in H. pylori-associated gastritis, as previous studies with IFNγ-deficient mice have shown." (PMID 29057967, 2017). "Although exogenous IFNγ treatment causes gastritis and parietal cell atrophy, the duration of treatment (28 days) is not sufficient to cause dysplasia." (PMID 24069395, 2013). "In a murine model of AIG, increased levels of IFNγ+ CD4+ T cells have been observed, a finding validated in the TxA23 mouse model, where IFNγ is directly involved in the death of gastric epithelial cells, leading to the development of chronic atrophic gastritis." (PMID 39193325, 2024). "and In vivo administration of IFNγ inhibitors was protective against gastritis induction." (PMID 39193325, 2024). "Notably, IFNγ promotes parietal cell atrophy with metaplasia during the progression of gastritis." (PMID 39193325, 2024). "H. pylori-specific CD4+ T-cells, together with prolonged IFNγ secretion, were shown to be indispensable for gastritis, as mice lacking either H. pylori-specific CD4+ T-cells or IFNγ did not develop gastric inflammation." (PMID 38343887, 2024).
preeclampsia (37 papers, 2010 to 2025). Preeclampsia is a hypertensive disorder of pregnancy that is characterized by new-onset hypertension with proteinuria presenting after 20 weeks of gestation, and depending on mild or severe forms may initially present with severe headache, visual disturbances, and hyperreflexia. "The pro-inflammatory cytokine, interferon gamma has been reported to be increased in the circulation (plasma and serum) of preeclampsia patients." (PMID 28008305, 2016). "Excessive Th1-type cytokines like interleukin (IL)-2, tumour necrosis factor-alpha (TNF-α) and interferon-gamma (IFN-γ) have been reported to be detrimental to foetus and associated with preeclampsia." (PMID 25257050, 2014). "Her working hypothesis assesses the miRNA-induced interferon-gamma (IFN-γ) pathway’s role in hematopoietic stem cell fate during preeclampsia." (PMID 39811734, 2024). "We observed an upregulation in interferon-gamma expression and a downregulation in transforming growth factor-beta-1 (TGF-β1), IL-4, and IL-10 in the placenta of patients with preeclampsia." (PMID 38894741, 2024). "Women with preeclampsia were found to exhibit increased concentrations of interleukin (IL)-1, IL-6, and tumor necrosis factor alpha (TNF-α) in their plasma and amniotic fluid, alongside elevated levels of IL-2 and interferon gamma (IFN-γ)." (PMID 41375625, 2025). "There was a slight reduction in the numbers of iNKT cells producing IFNγ in normal pregnant women compared to women with preeclampsia and the non-pregnant controls but this was not statistically significant." (PMID 20850184, 2010). "In preeclampsia, the shift away from type 1 responses either fails to occur or is reversed, with increased production of IL-18 and IFNγ relative to normal pregnancy." (PMID 20850184, 2010).
ischemic stroke (36 papers, 2011 to 2025). A stroke disorder caused by obstruction of blood flow to the brain, due to thrombotic (local blood clot formation) or embolic (due to a blood clot or other material traveling from another site) event. "For instance, the Th1 subpopulation promoted M1 polarization of microglia through secretion of pro-inflammatory factors, such as IFNγ, which accelerated the amplification of inflammation in ischemic stroke." (PMID 34248961, 2021). "For instance, CNS-specific type 1 T helper (Th1) cells secrete interferon gamma (IFNγ) following ischemic stroke to recruit immune cells into the CNS and activate cytotoxic CD8+ T cells, which exacerbate CNS damage by inducing apoptosis via caspase activation and Fas ligand signaling." (PMID 29895321, 2018). "The response to interferon-beta, interferon-gamma and GTP binding GO terms are both closely related to the protective effect against ischemic stroke." (PMID 35265682, 2022). "Previous studies have suggested that activated CD8+ T lymphocytes inhibit neural stem/progenitor cell proliferation via interferon-gamma (IFN-γ) and that activated regulatory T cells increase neurogenesis through IL-10 and TGF-β after ischemic stroke." (PMID 34262436, 2021). "Local expression of proinflammatory cytokines, particularly IFNγ and TNF, has been shown, in animal models, to worsen damage as incurred, for example, during ischemic strokes." (PMID 21941411, 2011). "A study compared the role of exosomes derived from interferon gamma (IFN-γ)-stimulating stem cells and control exosomes for treating ischemic stroke and found that IFN-γ preconditioning did not affect the secretion, but significantly altered the functional abilities of exosomes." (PMID 33869170, 2021).
metastatic tumors (36 papers, 2009 to 2025). "A gradually increased CSF1R from the inner tumors to the invasive fronts to the metastatic tumors was seen, whereas a trend of a decrease in IL-10 and IFNG was noted from the inner tumors to the invasive fronts to the metastatic tumors." (PMID 37586318, 2023). "Strikingly, all samples in control and PAC treatment groups, and 3/4 samples from IFNγ group, demonstrated a diffuse pattern of liver involvement with almost complete replacement of the organ by metastatic tumor." (PMID 35459800, 2022). "In order to determine if neo-antigen specific T cells were reflective of the presence of lung metastatic disease, we performed an IFNγ ELISPOT assay with lung draining lymph node cells (LDLNs)." (PMID 31601975, 2019). "Strikingly, the combination of IFNγ with subsequent administration of chemotherapy (PAC) led to limited metastatic disease (micrometastases) in vivo compared to the diffuse infiltration of the liver by metastatic tumors in the case of control and monotherapy with either IFNγ or PAC." (PMID 35459800, 2022). "Thus, 4T07 primary tumors prime systemic CD8+ T cells that induce cell cycle arrest of DCCs by IFNγ and TNFα and thereby prevent overt metastatic disease." (PMID 33536445, 2021). "Besides, class II HDAC inhibitors can selectively reprogram monocytes and macrophages in the tumor; reprogramming activates a robust antitumor immune response, mainly mediated by macrophages, CD8+ T-cells, and IFNγ, and reduces both primary and metastatic tumor burdens." (PMID 33959656, 2021). "Although Th1 cells are critical in sustaining an antitumor immune response via IFNγ signaling, we observe that high tumor Th1 versus TIL scores progressed to metastatic disease." (PMID 37534375, 2023). "miR-18a treatment led to increasing percentages of F4/80+IFNγ+, F4/80+IL-12+, F4/80+CD80+, and decreasing percentages of F4/80+ transforming growth factor beta (TGFβ)+, F4/80+CD206+ and F4/80+ IL-10+ detected in the liver metastatic tumor bearing mice." (PMID 27028860, 2016). "However, it revealed thereafter that the DC plus IFNγ treatment still not enough to elicit effective clinical outcomes against malignant tumor in the large size or progressive stage and metastatic tumors in which DCs and IFNγ is difficult to be directly injected." (PMID 29190690, 2017).
tetanus (36 papers, 2009 to 2025). A serious infectious disorder that follows wound contamination by the Gram-positive bacterium Clostridium tetani. "Furthermore, levels of PFOA were inversely associated with the interferon gamma (IFNɣ) production of ex-vivo lymphocytes after stimulation with tetanus and diphtheria toxoid, with an effect size of − 64 and − 59% (means Q1 vs. Q5), respectively." (PMID 32227269, 2020). "Infant malaria is associated with lower IFNγ, IL5 and IL13 (i.e. Th1) responses to both BCG and tetanus immunisation." (PMID 29124321, 2017). "Influenza-specific IL-2+/- IFNγ+ cells were used as committed Th1 cell controls, and tetanus-specific 2+γ- cells as uncommitted Thpp cell controls." (PMID 24788814, 2014). "Tetanus also stimulated a substantial population of Tbet- IL-2- IFNγ- TNFα+ cells, consistent with stochastic expression of IL-2 in the Thpp as well as the Th1 population." (PMID 24788814, 2014). "One study reported substantial differences in cytokine responses (interferon gamma and interleukin [IL]-13) to mycobacterial vaccine antigen (purified protein derivative) and cytokine (IL-13) and antibody (IgG) responses to tetanus between rural and urban settings in Uganda." (PMID 39424574, 2024). "Furthermore, PFOA levels were shown to be inversely related to the interferon gamma (IFN-γ) production of ex-vivo lymphocytes after stimulation with tetanus and diphtheria toxoid." (PMID 35202231, 2022). "T cell activation was assessed by measurement of intracellular cytokines (IL-2, IFNγ, TNFα) following stimulation of peripheral blood T cells with PHA, a tetanus and diphtheria cocktail, PPD, anti-CD3, or SEB." (PMID 39061230, 2024). "In cultures stimulated with CMV, EBV, influenza and tetanus peptides, the CD4+ T‐cell count correlated with IL‐1β (P = 0.045) and CD8+ T‐cell count with IFNγ (P = 0.013) and IL‐1β (P = 0.012)." (PMID 30323928, 2018). "Of note, only maternal Mansonella perstans infection was associated with significantly higher IL10 responses to BCG and tetanus immunisation but with no reduction in IFNγ, IL5 and IL13 responses." (PMID 29124321, 2017).
autism (34 papers, 2011 to 2025). Persistent deficits in social interaction and communication and interaction as well as a markedly restricted repertoire of activity and interest as well as repetitive patterns of behavior. "In other studies, IFNγ levels have been found to be increased in the brains and blood of individuals diagnosed with autism as well as in a mouse model of autism." (PMID 29422905, 2018). "They reported that children with autism considerably generated TIM-3, CD11a,b, CD14, chemokine receptor type 5 (CXCR5), interleukin 1B (IL-1B), and interferon-gamma (IFN-γ) related mRNA, and protein expression levels in contrast to control children." (PMID 33269154, 2020). "The Th1-Th2 paradigm, that is immune skewing toward type-1 cell-mediated immunity (interferon-gamma promoted immunity) vs. type-2 humoral immunity (IL-4, IL-5 and IL-13 promoted immunity), may not be properly applicable to immune alterations in autism." (PMID 21799730, 2011).
cardiomyopathy (34 papers, 2010 to 2026). A disease of the heart muscle or myocardium proper. "Application of clinically used JAK/STAT inhibitors, tofacitinib and baricitinib, fully prevented IFNγ-induced cardiomyopathy, confirming the critical roles of this signaling pathway in inflammatory cardiac disease." (PMID 37035738, 2023). "Higher frequencies of CD4+ IL-17A+ T-cells, lower levels of IL10 and IL10, and higher levels of IFNγ and TNFα are observed in individuals with more severe cardiomyopathy." (PMID 33193300, 2020). "Pro-inflammatory cytokines including tumor necrosis factor-α (TNF-α), interferon gamma (IFN-γ) and interleukin-6 (IL-6) appear to make a significant contribution to the pathophysiology of cardiomyopathy and heart failure." (PMID 31998452, 2019). "The participation of IFNγ in the cardiomyopathy induced by immunization with pcDNA3-hM2 plasmid was assessed through the dosage of this cytokine in heart homogenates." (PMID 26592184, 2015). "This would confirm the role that certain inflammatory cytokines (IFNγ, TNFα, or CCL3) play in the induction of cardiac pathologies (cardiomyopathy and QTc prolongation) in the disease." (PMID 40623042, 2025). "Based on the data presented above, we speculate that CD8+IFNγ+ and CD8+Pfn+ T-cells play distinct roles in the T. cruzi-elicited cardiomyopathy." (PMID 22532799, 2012).
endotoxemia (34 papers, 2010 to 2026). "The cytokine profiles revealed that the adoptive transfer of M(IFNγ+LPS+IC) in mice with LPS-induced endotoxemia before LPS administration has a systemic impact on some pro-inflammatory cytokines but no detectable influence on IL-10." (PMID 31998290, 2019). "To evaluate the impact of M(IFNγ+LPS+IC) in vivo, we tested the effect of adoptive transfer of M(IFNγ+LPS+IC) on the systemic cytokine profiles in an LPS-induced endotoxemia model." (PMID 31998290, 2019). "Experimental observations indicate that IL-22 application in murine endotoxemia fails to significantly affect production of the pro-inflammatory cytokines TNFα, IL-6, and IFNγ analyzed in the early phase (up to 8 h after onset of endotoxemia) of the syndrome." (PMID 23382730, 2013). "Finally, the effect of M(IFNγ+LPS+IC) on systemic cytokine production was tested in an LPS-induced endotoxemia model by adoptive transfer approach." (PMID 31998290, 2019). "Finally, we investigated the impact of M(IFNγ+LPS+IC) on the systemic immune response by adoptive transfer of M(IFNγ+LPS+IC) in an LPS-induced endotoxemia model." (PMID 31998290, 2019). "As a consequence, the NK compartment potentially produced reduced levels of IFNγ which was shown to strongly potentiate TNF production and mortality during experimental endotoxemia." (PMID 31849939, 2019).
myocardial infarction (34 papers, 2013 to 2026). Gross necrosis of the myocardium, as a result of interruption of the blood supply to the area, as in coronary thrombosis. "We also found and replicated biallelic combinations of TGFB1 with FGB, TGFB1 with CRP and IFNG with PTGS1 genetic variants associated with myocardial infarction providing a detectable cumulative effect." (PMID 26658659, 2015). "Interestingly, rs10080815 (chr6:160687412:T > G) overlaps an IFNγ-upregulated peak and is shared in four cardiac diseases (angina pectoris, myocardial infarction, chronic ischemic heart disease, and coronary atherosclerosis)." (PMID 40104808, 2025). "So, here, we hypothesize that the presence of IL6 in EV-CDCs, as well as the increase in IFNγ/EV-CDCs, may have a therapeutic effect in the control of acute inflammatory responses in myocardial infarction." (PMID 32582685, 2020). "The genetic impact of TGFB1, FGB, CRP, IFNG, and PTGS and/or their biallelic combinations on myocardial infarction was found and replicated in Russians." (PMID 26658659, 2015). "Interferon γ (IFNγ) + T cells did not suffer significant changes 1 h after myocardial infarction, when compared to the control." (PMID 30898123, 2019).
osteoporosis (34 papers, 2012 to 2025). A condition of reduced bone mass, with decreased cortical thickness and a decrease in the number and size of the trabeculae of cancellous bone (but normal chemical composition), resulting in increased fracture incidence. "Studies indicate that elevated levels of IFNG are associated with increased osteoclastogenesis, which leads to enhanced bone resorption and contributes to the development of osteoporosis, particularly in postmenopausal women." (PMID 40919176, 2025). "Among cytokines regulating bone metabolism, interferon G (IFNG) has been shown to play an important role in the regulation of osteoporosis." (PMID 35581339, 2022). "IFNγ can be an effective anabolic treatment for osteoporosis as in the bone micro-environment it is secreted by MSCs to promote osteogenic differentiation." (PMID 33413646, 2021). "A sclerostin (SOST) antibody and interferon γ (IFNγ) also have therapeutic potential in treatment of osteoporosis." (PMID 33413646, 2021). "The cytokine interferon-gamma (IFN-γ), a member of the interferon family, is an important factor in the etiology and treatment of osteoporosis because it mediates bone remodeling." (PMID 38817601, 2024). "By inhibition of the Wnt pathway, these proteins along with several other cytokines, such as IL‐15, interferon gamma, IL‐17 MCP‐4 (monocyte chemoattractant protein), and TNF‐α blunt the bone formation there by leading to osteoporosis and its sequelae." (PMID 36911094, 2023). "Osteoporosis is mediated by a variety of inflammatory mediators, including TNF-α, RANKL, interleukin 1 beta, IL-6, and interferon gamma." (PMID 35187034, 2022).